IDH2 (isocitrate dehydrogenase (NADP(+)) 2)
Diseases named in the same sentence as IDH2 in open-access papers (continued):
Sharing a sentence is not in itself a finding about the gene and the disease.
tumor (continued). "If in fact (R)-2-HG is inhibiting tumor growth, as reported in this study and by another group, inhibition of mutant IDH2 enzymes may in actuality promote cancer progression." (PMID 31105869, 2019). "Primary AML tumor samples were selected based on having known HLA haplotypes for HLA-A, B, C and HLA-DR, and at least one or more common recurrent mutations in either NPM1, FLT3, DNMT3A, IDH1, IDH2, KIT, or RAS from previous clinical evaluation." (PMID 31291378, 2019). "Finally, inducible IDH2 silencing enhanced the therapeutic efficacy of PI carfilzomib in a subcutaneous xenograft model of MM, resulting in inhibition of tumor progression and extended survival." (PMID 31010244, 2019). "Finally, it has been suggested that IDH2 expression in the tumor microenvironment can influence tumorigenesis." (PMID 31010244, 2019). "Interestingly, the level of serum IDH2 decreased in patients with NSCLC at about 1 week after surgical removal of the tumor." (PMID 29465809, 2018). "Not only can these clones be statistically explained with allele dropout, but they also do not fit with a model of serial mutation acquisition predicted by the presence of the NRAS, ASXL1, and IDH2 triple-mutant clone comprising 64% of the tumor at this time point." (PMID 30087104, 2018). "This can serve as a surrogate marker for all tumor relevant IDH1 and IDH2 mutations." (PMID 29499756, 2018). "Therefore, XAF1 methylation does not represent an independent prognostic marker in this particular tumor entity but provides a surrogate marker of IDH1 and probably IDH2 mutations." (PMID 28122345, 2017). "IDH2 was recognized as cancer genes in a study involving 21 tumor types." (PMID 28993730, 2017). "The only IDH1R132H negative tumour which otherwise fulfilled the WHO 2016 criteria for OII was mutated for IDH2 on complementary molecular analysis (data not shown)." (PMID 28030632, 2016). "Mutations in the Sdh genes as well as gain-on-function mutations in the Idh1 or Idh2 genes should be excluded in this case, due to the absence of clonality in the non-tumor liver tissue, in contrast to tumors." (PMID 25918251, 2015). "IDH2 expression only correlated with tumor differentiation (P =0.017)." (PMID 24716838, 2014). "In summary, 5-hmC and IDH2 correlate with less aggressive tumor behavior in HCC." (PMID 24716838, 2014). "That’s important for two reasons: first – because the tumor is more likely to be lower grade, that is, less aggressive, if there is a mutation in IDH1 or IDH2; and second – drugs have now been developed specifically to inhibit the mutant isoforms of IDH1 and IDH2 that occur in these tumours." (PMID 24581008, 2014). "5-hmC and IDH2 correlate with less aggressive tumor behavior in HCC." (PMID 24716838, 2014). "When such tumours arise as solitary lesions in the medullary cavity (central CS) or more rarely in the periosteum, ~50% harbour either a somatic IDH1 (isocitrate dehydrogenase 1) or IDH2 heterozygous mutation." (PMID 23863747, 2013). "Patients with D-2-hydroxyglutaric aciduria, a rare metabolic condition in which high levels of D-2HG occur due to mutations in the D-2HG dehydrogenase gene D2HGDH or in IDH2, do not show increased levels of tumor development." (PMID 24252742, 2013). "Tumours negative for IDH1 mutations frequently exhibited mutations at the analogous amino acid (R172) of the IDH2." (PMID 23998913, 2013). "We hypothesized that if IDH1 and IDH2 functioned as tumor suppressor genes, then some tumors may exhibit dense hypermethylation of the CpG island associated with their promoter region." (PMID 23267435, 2012).
tumor (continued). "The mouse model used in this study was IDH1 and IDH2 wild-type, thus our findings revealed that combining gemcitabine with radiation was efficacious in reducing tumor burden and prolonging median survival when compared to radiation or gemcitabine alone in this class of GBM." (PMID 22536446, 2012). "Taken together, these findings suggest that at least in some circumstances IDH1 and/or IDH2 may function as a typical tumor suppressor gene." (PMID 23267435, 2012). "This evidence suggests that the epigenetic mechanism underlying the inhibition of tumor suppressor genes may be independent of the hypermethylated state induced by IDH1/IDH2 mutation." (PMID 39123479, 2024). "However, the mechanisms through which IDH2 influences macrophage polarization and modulates tumor growth remain unknown." (PMID 39256649, 2024). "Interestingly, wild-type IDH2 is highly expressed in various cancers, including glioblastoma, lung, breast, esophageal, colorectal, and hepatocellular carcinomas and has been shown to promote tumor growth and therapy resistance." (PMID 39409901, 2024). "In addition to the good correlation between the VAF on bulk tumor sequencing and the VAF of the sub-clones harboring FLT3-ITD and IDH2 mutations, rare mutations that were below the detection limit of bulk tumor sequencing were detectable with sc-DNA sequencing." (PMID 35563039, 2022). "In Case 9, the primary tumor had IDH2 mutation, and the secondary tumor did not." (PMID 35505351, 2022). "The amount of carnitine derivatives, including propionylcarnitine, is lower in IDH1 and IDH2 mutants, which can contribute to increased fatty acid synthesis, decreased oxidation of certain fatty acids, and accelerated proliferation of cancer cells and tumor growth." (PMID 35053475, 2022). "These mutations have been found not only in tumor cells from patients with T-cell lymphoma but also in multiple lineages of normal bone marrow and blood cells, including B cells, myeloid cells, and myeloid progenitor cells, whereas RHOA and IDH2 mutations are confined only to tumor cells." (PMID 36428791, 2022). "Compared to the initial grossly resected tumor specimen, the recurrent tumor possessed loss of heterozygosity of 1p, 10q, 17q, and 19q chromosomes, as well as a new C228T TERT promoter mutation, while the status of wild-type IDH1/IDH2 and mutant BRAF V600E was unchanged." (PMID 36703629, 2022). "Wang’s study shows that silencing of IDH2 in prostate cancer cells increases glucose consumption and lactate production as well as the production of ROS and leads to the expression of the HIF1a pathway with increased tumor cell invasion but reduces the tumor cell proliferation and tumor volume." (PMID 34948229, 2021). "The WRN gene was recognized as a tumor-suppressor gene and evidence suggests that it plays a role in promoting oncogenic proliferation which may likely contribute to AML transformation in Patient 5, in addition to the NPM1 and IDH2 mutations." (PMID 34560908, 2021). "Thus, our findings show that despite their shared (R)-2-HG production, IDH2 mutations are not alike and differ in shaping tumor cell behavior and response to chemotherapeutic agents." (PMID 31105869, 2019). "Thus, SLC25A1 and IDH2 might cooperate in adaptive metabolic processes that allow cancer cells to cope with the adverse conditions in the tumor microenvironment." (PMID 29888201, 2018). "Unless that mutation is too frequent to occur by simple coincidence in that type of tumor, labeling IDH1 R132 or IDH2 R172 mutations as driver ones in a tumor not frequently seen to harbor them and without proving the high content of (D)-2HG in that tumor, should be advised against." (PMID 28785398, 2017).
tumor (continued). "Another known pathway where tumor cells maximize citrate synthesis, is through the excessive utilization of glutamine and glutamate to produce 2KG, an indirect precursor of citrate through the reductive carboxylation reaction catalyzed by IDH2 within the mitochondria and IDH1 within the cytosol." (PMID 28785398, 2017). "Moreover, a direct correlation between the amount of 2HG produced by mutant IDH1/2 and the characteristics of the resulting tumor seems to exist, since patients with IDH2 R140-mutant AML produce lower levels of D-2HG and have a better prognosis those with IDH2 R172 mutations." (PMID 26948489, 2015). "The 2-HG levels, measured using MRI, correlate 100% with whether the tumor has a mutation in IDH1 or IDH2, again without the need to get any tissue." (PMID 24581008, 2014). "So it becomes possible to tell the patient on the day of the MRI scan whether or not there is an IDH1 or IDH2 mutation in the tumour." (PMID 24581008, 2014). "Since these data were based on whole genome sequencing that could overlook specific mutations, we performed targeted sequencing in the tumor (TCGA-B6-A1KF) with very high levels of 2-HG to look for the recurrent mutations found in other tumors in IDH1 and IDH2." (PMID 25091696, 2014). "Sequencing of IDH1 and IDH2 was negative for mutation in either tumor sample (data not shown)." (PMID 23047041, 2012). "Understanding the unique DNA and histone methylation features among different tumor tissue and among different IDH1 and IDH2 mutants remain important areas of research." (PMID 40188944, 2025). "Multiple approaches were then employed to evaluate the role of wild-type IDH2 expression in TNBC cell proliferation in vitro and tumor growth in vivo." (PMID 38658533, 2024). "A third investigation supports these findings, demonstrating that IDH2 inhibition in CAR T cells reduces exhaustion, enhances memory T cell formation, and improves anti-tumor efficacy." (PMID 39409901, 2024). "While promoting the degradation of IDH2, D-mannose can inhibit the production of NADPH as well, thus rendering the tumor cells more sensitive to the pro-oxidant BSO treatment." (PMID 38167476, 2024). "NGS of the tumor biopsies from the initial diagnosis and from the relapse from March 2022 revealed that the tumor was IDH1 and IDH2 wild type and harbored an FGFR3-TACC3 fusion." (PMID 39211518, 2024). "Tumours of this family show a diffuse histology with features of malignancy, and are wildtype for histone H3, IDH1, and IDH2." (PMID 39126064, 2024). "The results showed the expression of tumor malignant characteristic genes such as CDKN2A CKS1B, HSPA9, IDH2, and MYC among different subpopulations of plasma cells, with high expression in plasma cell_2." (PMID 39271659, 2024). "We observed that CD8+ T cells located within tumor islets showed higher expression of several mitochondrial proteins (TOM20, IDH2 and ATP5a) compared to CD8+ T cells located in the surrounding stroma." (PMID 38467616, 2024). "These tumor markers include IDH1 R132, IDH2 R172, pTERT C228 and C250, H3F3A K27/G34, Hist1H3B K27, and BRAF V600." (PMID 39606159, 2024). "Overall, the effect of PTPN12, IDH2, P2RX4, and KDELR2 on tumor immune cell infiltration is a complex process that typically involves multiple molecular pathways and signaling pathways." (PMID 37563735, 2023). "IDH1 and IDH2 have more than 70% homology, and a recent report found that IDH1/2 is closely related to tumours." (PMID 37108242, 2023). "In our study, we demonstrated that in OC, EZH2 transcriptionally upregulated IDH2 to potentiate metabolic rewiring by enhancing tricarboxylic acid cycle (TCA cycle) activity, which provide a novel mechanism by EZH2 to promote tumor growth." (PMID 37210576, 2023). "Notable differences in the protein expression levels of ATPase, IDH2, LDHA, and SIRT1, as well as mtDNA amount, were detected between the samples of non-tumor adjacent tissue and tumor tissue from metastatic CRC patients." (PMID 35205159, 2022).
tumor (continued). "Decreased SIRT3 was found to decrease IDH2 and SOD2 hyperacetylation by increasing the level of reactive oxygen species, suggesting that SIRT3 acts as a tumor suppressor in B cell malignancies." (PMID 36230534, 2022). "In G2/3 tumours, the activity of SBS5 was similar in IDH1 and IDH2, but lower in IDHwt (IDH1 vs IDH2 p = 0.4, IDH1 vs IDHwt: p = 0.03)." (PMID 36042521, 2022). "We showed that patient age at diagnosis increased across grades in these groups and that the median age was highest in those with IDH2 tumours (IDH1: 55 year, IDH2: 67 year, IDHwt: 47 year, IDH1 vs IDH2: p = 0.003, IDH1 vs IDHwt: p = 0.0006)." (PMID 36042521, 2022). "Tumor cells with wild-type IDH1 and IDH2 were found to contain an average of 3.41 μg of 2-HG per gram of tumor tissue." (PMID 35154988, 2022). "GD was highly enriched in IDHwt tumours (GD%, IDH1: 24%, IDH2: 9%, IDHwt: 63%, IDHwt vs IDH1 p = 0.0005), and HP was exclusive to this group (HP%, IDH1: 0%, IDH2: 0%, IDHwt: 37%, IDHwt vs IDH1 p = 8e-5)." (PMID 36042521, 2022). "Overview of correlation of tumour grade, IDH1, IDH2 and GNAS mutant profile pre‐ and postoperatively." (PMID 34528398, 2021). "Their prevalence is different according to the cancer type since it was found that IDH1 has higher incidence rate than IDH2 in brain cancers, while in AML they are equally common, likely reflecting the differential tumour metabolic needs." (PMID 34070384, 2021). "The full face tissue sections demonstrated an even staining of IDH2 expression within IBC and DCIS, indicating that TMA cores are representative for the whole tumour when assessing IDH2 expression." (PMID 31599393, 2020). "In patient 9, SMO, NTRK3, IDH2, IGF1R, and CDK12 were also amplified in tumour #1 in addition to ERBB2 amplification." (PMID 31929516, 2020). "IDH2 was upregulated in both human SCCs and AdCs, whereas all three isoforms were upregulated in MYC+N1ICD tumours." (PMID 31114017, 2019). "For 7 SCC-distinguishing enzymes (ASNS, GAPDH, GOT2, IDH2, ME1, PSAT, and TPI) protein levels were increased in MYC+N1ICD tumours compared with the normal lungs." (PMID 31114017, 2019). "Thus, PIK3CA, NRAS, HRAS, PTEN, MET, and IDH2 R140Q mutations might be related to the metastasis process rather than primary tumor development." (PMID 29290998, 2017). "Strikingly, and counterintuitively to the anti-tumor activity of DIO1, restoration of DIO1 expression resulted in moderate increase of TKT, NAMPT and IDH2 protein levels." (PMID 29272308, 2017). "As a further line of interest, the detection of elevated D2HG concentrations in different tumor entities may identify elevated D2HG levels as a surrogate marker, eventually in combination with the distribution of lactate, for tumor-relevant IDH1 and IDH2 mutations." (PMID 27014623, 2016). "IDH2 expression correlated with HBsAg (P =0.015), AFP (P <0.001), and tumor differentiation (P =0.015)." (PMID 24716838, 2014). "We also detected significant correlations between low IDH2 expression and HBsAg background, a high level of AFP, and low-grade tumor differentiation." (PMID 24716838, 2014).
tumor (continued). "Here, we show for both the IDH2 and IDH3A/IDH3B genes expression is mainly correlated in tumor samples exhibiting deleted copy number to normal copy number." (PMID 22174824, 2011). "IDH2-mutations were associated with significantly worse DSS compared to IDH-wild-type or IDH1-mutated tumors, independent of tumor grade." (PMID 41906217, 2026). "In addition, overexpression of FOXO1 or manipulation of T cell metabolism by targeting isocitrate dehydrogenase 2 (IDH2) has been shown to facilitate the generation of memory-like CAR-T cells and improve their anti-tumor activity in vivo." (PMID 40755764, 2025). "Significant increases in gene expression of GFAP (4-fold), a type III intermediate filament in astrocytes, and IDH1 (5-fold) were observed in tumour samples, with no observed changes in IDH2 expression." (PMID 41034696, 2025). "The tumor exhibited no IDH1, IDH2, TERT, H3, or BRAF mutation, and had no EGFR amplification, no MYB rearrangement, and a positive MGMT status." (PMID 39227460, 2024). "Mutation analysis using WES data and CNV analysis using methylation classifier data from tumor tissues revealed no mutations in IDH1, IDH2, BRAF, or histone H3 genes (H3F3A, HIST1H3A, HIST1H3B, HIST1H3C, and HIST2H3C) in all tumors." (PMID 38605367, 2024). "Genes involved in glycolysis (ALDOA, LDHA, PGK1, PFKL, PGM1) and other metabolic processes (GPX4, PRDX4, ACO2, ASPH, IDH2, SQLE, NPC2, SPTSSA) were upregulated in primary tumor cells, suggesting that the metabolism in primary tumors was distinct from that in their matched metastasis." (PMID 39225101, 2024). "However, both investigations have limitations, including an incomplete understanding of metabolic adaptations post-IDH2 inhibition and the dynamics of memory CAR T cells in specific tumor models." (PMID 39409901, 2024). "We then tested if the elevated α-KG could mediate the therapeutic effect of IDH2 inhibition in animals, using the cell-permeable compound DM-α-KG for the treatment of mice bearing MDA-MB-231 tumor xenografts." (PMID 38658533, 2024). "The results showed that both TNBC and non-TNBC tumor tissues expressed significantly higher levels of IDH2 protein compared to the normal breast tissues, with the highest level observed in TNBC tumor tissues." (PMID 38658533, 2024). "In the initial proof-of-principle experiments, we showed that specific silencing of IDH2 could profoundly inhibit TNBC cell proliferation and induced apoptosis in culture, and could effectively suppress tumor growth in vivo." (PMID 38658533, 2024). "Among them, ERBB4 and NPM1 are presumably involved in cSCC tumorigenesis; in addition, GNAQ, GNAS, JAK2, NRAS, IDH2, and CTNNB1 may be related to tumor metastasis." (PMID 36780540, 2023). "In these datasets, we found only one case of IDH2-mutant and 1p/19q non-codel tumor, but CNA was not analyzed in this case." (PMID 38012788, 2023). "These neoplasms feature a characteristic and similar, but not identical, mutational landscape with mutations in epigenetic modifiers (TET2, DNMT3A, IDH2), RHOA, and T-cell receptor signaling genes." (PMID 36793612, 2023). "In tumours, rather than reactivating IDH2 and IDH3, cancer cells remain dependent on this highly active cytoplasmic IDH1." (PMID 37086156, 2023). "Using all available clinical information (n = 342), we found that IDH2 tumours tended to be larger at time of presentation (IDH1 vs IDH2: p = 0.001, IDH1 vs IDHwt: p = 0.4), supporting the premise that these tumours evolve over longer time periods, and present in older people." (PMID 36042521, 2022). "In line with this, the molecular landscape of human iCCA includes a subgroup of tumours with oncogenic IDH1 and IDH2 mutations; genetic variants which are not observed in extrahepatic biliary tract tumours." (PMID 35986087, 2022).